INS (insulin)
Diseases named in the same sentence as INS in open-access papers (continued):
Sharing a sentence is not in itself a finding about the gene and the disease.
tumor (continued). "PBMR1 mutant tumours are associated with increased activity of TFs/(phospho)proteins that have roles in interleukin signalling and MYC, while regulators with increased activity in BAP1 mutant tumours are involved in DNA damage response, apoptosis, insulin signalling and mTOR signalling." (PMID 28139702, 2017). "Insulin or IGF-1 treatment stimulates the proliferation of tumor cells." (PMID 28978182, 2017). "The PI3K pathway may mediate the sensitivity of selected tumours to dietary restriction as tumours sensitive to dietary restriction were growth-responsive to insulin and IGF1 whereas tumours with constitutively active PI3K signalling were not." (PMID 28316059, 2017). "Further, our findings suggest a bidirectional relationship between dysregulated glucose/insulin metabolism and BCa, as both, tumor- and IR-related markers are correlated with the severity of glucose/insulin metabolism impairment in overweight/obese premenopausal BCa patients." (PMID 29113405, 2017). "However, we cannot fully exclude the effect of direct insulin analogue treatment on tumor cell metabolism, since treatment of MCF7-IGF1R cells with the various insulin analogues also affected the glycolytic metabolic program." (PMID 28173837, 2017). "Moreover, the average tumor size was significantly larger in the STZ/INS-treated mice than in the STZ-treated mice." (PMID 28903776, 2017). "PE may act in many different ways on tumor tissue such as e.g. altering levels of blood glucose, ketone bodies, sex hormones and insulin, as well as stimulating the immune system." (PMID 27447560, 2016). "Other hypothesis, which deserves further investigation, is that the growing tumor induces FGF21-mediated insulin secretion which leads to an increased uptake of glucose by the tumor to sustain its energy requirements and growth." (PMID 27358750, 2016). "Alternatively, tumours might induce hyperglycaemia by enhancing insulin resistance and hepatic gluconeogenesis, thus providing extra glucose required for tumour growth." (PMID 26843513, 2016). "High insulin and leptin levels seem to have a role modulating the growth of these tumours." (PMID 27415018, 2016). "Furthermore, a recent study of diet-induced obese mouse demonstrated that addition of metformin not only normalized insulin levels but also enhanced anti-tumor immunity." (PMID 26967162, 2016). "In contrast to the tumor-promoting effects induced by high-calorie diets, dietary restriction (DR) decreases the growth of various types of tumors in rodent models through reduced systemic insulin and IGF-1 signaling." (PMID 27604692, 2016). "Second, it may act indirectly on target cells by regulating inflammatory responses, influencing tumor angiogenesis, and modulating insulin sensitivity." (PMID 26729407, 2016). "Hence, these authors find that there is a positive correlation between TRIB3 and activation of insulin signaling in tumor tissues." (PMID 27038142, 2016). "Increased levels of circulating insulin and/or glucose might elicit additional effects on tumor migration and metastasis." (PMID 27604692, 2016). "After tumor excision, serum levels of glucose, insulin, and C-peptide normalized." (PMID 27957352, 2016). "It is possible that metformin could maintain the insulin level close to the control group values; in our previous finds, we verified maintenance of insulin content in tumour-bearing rats treated with higher metformin dose." (PMID 27388367, 2016). "In our hands, such diabeto-biguanide activity modestly affected the growth of insulin-independent breast xenotumors, reaching a maximum of 43% at 4 weeks after inoculation of tumor cells and decreasing to 30-35% reduction toward the end of the treatment period." (PMID 27356748, 2016). "Together with the well-documented mitogenic effects of insulin, these studies lead to the hypothesis that increased insulin levels might play an important role in tumor formation and progression in obese individuals." (PMID 27604692, 2016).
tumor (continued). "Normal and tumor cells respond to metabolic hormones, such as leptin and insulin." (PMID 27842582, 2016). "Moreover, to avoid an insulin response and adsorption by the liver, 2-DG is delivered by slow-release pump yielding significant anti-tumor control when combined with FF." (PMID 27183907, 2016). "It responds to insulin, and its altered expression in tumor cells may allow both glucose uptake and phosphorylation of Akt and FOXO1 in adipocytes." (PMID 27551267, 2016). "This happened because normal cells became insensitive to insulin, but the tumor cells didn't." (PMID 26573956, 2015). "However, when patients were considered individually, those exhibiting the largest reductions in serum insulin, tumor IR expression and p-Akt (as a summary variable) exhibited the largest reductions in tumor cell proliferation (r = 0.41, P = 0.012)." (PMID 25849721, 2015). "As the anamorph of O. sinensis, H. sinensis has activities to modulate immune responses, inhibit tumour cell proliferation, enhance hepatic function, regulate insulin sensitivity and decrease plasma cholesterol levels, this makes it become more and more valuable in pharmacology." (PMID 25765329, 2015). "During the three months period of 2-DG administration prior to tumor implantation, we observed a marginal decrease in the blood glucose level with a significant reduction in serum insulin concentration indicating increased insulin sensitivity." (PMID 26135741, 2015). "Dietary 2-DG could also reduce the insulin levels in the tumor bearing mice, where the insulin levels in the tumor bearing control mice increased > 2 folds compared to the non tumor bearing control mice." (PMID 26135741, 2015). "It is generally accepted that during tumor progression an inflammatory response operates locally promoting systemic changes, among which a sustained decline in insulin sensitivity would allow the redistribution of glucose from major consumers (e.g. skeletal muscle) to tumor cells." (PMID 25897425, 2015). "However, tumor cells harboring activating mutations in PI3K were found to be resistant to caloric restriction, despite the reduction in insulin and IGF-1 levels." (PMID 26192445, 2015). "In addition to inhibiting insulin release and elevating blood glucose levels, somatostatin analogues also have anti-proliferative and tumour-stabilising effects." (PMID 25755880, 2015). "All together, the results of this systematic review suggest that insulin treatment might be involved in tumour promotion." (PMID 26242987, 2015). "To validate the dysfunctions of autophagic and UPS clearance as molecular mechanisms connecting TRB3 to insulin/IGF-induced tumour development, we examined whether the inhibition of autophagy or UPS might reverse the antitumour effects of TRB3 depletion." (PMID 26268733, 2015). "During hospitalization, endocrine examinations were compatible with an insulin-producing tumor." (PMID 25816027, 2015). "Furthermore, in an important analysis, when patients were assessed individually, the largest decreases in serum insulin, tumor IR, and p-Akt (via a summary score of all three variables) correlated with the largest decreases in tumor cell proliferation." (PMID 26111812, 2015). "Moreover, our observations also show that 2-DG mimics some of the effects of DER such as reduction in the core body temperature, serum insulin levels and tumor cell proliferation together with modulation seen in the host immune system and ECM." (PMID 26135741, 2015). "Controversy surrounds whether metformin's antitumorigenic benefits stems from its indirect effects via decreasing circulating insulin and glucose levels or its direct effects in tumor cells via AMPK activation and inhibition of the mTOR pathway." (PMID 25417601, 2015). "In contrast, insulin is produced solely by the pancreatic beta cells, except in very rare cases, so serum insulin is a relatively good measure of the level of insulin signaling occurring at the tumor site." (PMID 26029167, 2015).
tumor (continued). "Also very well known is the effect of caloric restriction (which dramatically reduces IGF1 and enhances insulin sensitivity) on reducing the incidence of spontaneous and chemically-induced tumours in rodents." (PMID 26284118, 2015). "Furthermore, cathepsin L expression was limited to the insulin-producing cells in the tumor tissue, indicating a beta-cell origin of cathepsin L expression in the MycERTAM;Bcl-xL tumor model." (PMID 25927437, 2015). "A detailed protein expression analysis showed that tumours induced by AspB10 or IGF1 have a distinct expression pattern compared to tumours from insulin- or vehicle-treated mice; both the PI3K and the MAPK were found to be significantly upregulated after AspB10 and IGF1 treatment." (PMID 26242987, 2015). "Expression of the IR, coupled with the decrease in PKB/Akt and ERK1/2 activity in metformin-treated tumors, supports a model whereby lowering of systemic insulin leads to decreased IR stimulation on tumor cells and a subsequent reduction in downstream signaling, cell proliferation and survival." (PMID 25849721, 2015). "Decrease in insulin levels, may be partly responsible for the anti-tumor effect, thereby reducing the rate of tumor growth as observed from the reduced BrdU and PCNA staining in the tumors of 2-DG fed mice, indeed supporting this proposition." (PMID 26135741, 2015). "Additional biological activities such as pro-angiogenesis, pro-migration and pro-glycolysis may also account for the insulin/IGF-induced tumour development." (PMID 26268733, 2015). "Moreover, glucose uptake was also inhibited after TZL treatment in a PKCθ-dependent manner (5 μM, 16 h), suggesting that TZL limits tumor cells access to glucose by inducing an insulin resistant phenotype via activation of PKCθ." (PMID 26298773, 2015). "Indeed, hematopoietic stem cells or progenitor cells require several growth factors, such as insulin, IL-3, IL-6, G-CSF and GM-CSF, but these are dispensable for the culture of tumor initiating cells." (PMID 24466252, 2014). "Insulin inhibition may be less effective in later stages of tumor progression as genetic and epigenetic alterations accumulate and chronically activate the PI3K−Akt−mTOR pathway." (PMID 25364576, 2014). "Besides a tumor cell-specific effect, metformin has a systemic antiproliferative effect by lowering circulating glucose and insulin levels, contributing to tumorigenesis." (PMID 24924771, 2014). "In view of the lifelong exposure and large patient populations involved, insulin analogs with an increased mitogenic effect may potentially constitute a major health problem when inducing the growth of pre-existing neoplasms." (PMID 24904529, 2014). "This could be indicative of the progression of an invasive tumor cell population that has lost insulin expression, and gained Id1 expression." (PMID 23691228, 2013). "The mechanism for this phenomenon remains unclear, ranging from increased levels of the promitogenic factor insulin to decreased chemotherapy delivery to the tumor due to altered microvasculature." (PMID 24133632, 2013). "In conclusion, our findings strongly support that Insulin/IGF-I signaling is an appealing target with implication in the modulation of glycosylation of key molecules involved in tumor invasion, having therefore promising therapeutic aplications in epithelial cancers." (PMID 24282611, 2013). "MiR-33b regulates fatty acid oxidation and insulin signaling, and therefore may play a role in tumor metabolism." (PMID 24143167, 2013). "The indicated anti-neoplastic activity of metformin may relate to reduced plasma insulin concentrations or by direct effects on the tumour cells." (PMID 23663483, 2013). "Finally, knockout of PTEN and TSC, both well-known tumor suppressors, greatly increased insulin-driven protein synthesis." (PMID 24062690, 2013).
tumor (continued). "In fact, the low levels of insulin could be a contributing factor involved in the lower tumor growth observed in PAC120 PCa mice treated with STZ used in the present study." (PMID 24058525, 2013). "Insulin has been known to have a mitogenic activity and theoretically could have a promoting effect on the growth of tumor cells." (PMID 24224094, 2013). "However, it would be limited in tumours where cell proliferation or survival was supported by the local action of insulin itself." (PMID 23826179, 2013). "In addition to insulin and IGF-I, over-expression of IGF-II, a hormone produced in the liver, is also associated with tumour development." (PMID 24073332, 2013). "Evidence suggests that insulin stimulates the proliferation of various cell types through different mechanisms; for example, stimulating smooth muscle cells and tumor cell lines (HT29, SW480 and MCF-7) by Akt and Erk phosphorylation, while promoting 3T3-L1 adipocyte proliferation through MAPKs." (PMID 23110176, 2012). "However, experimental data indicate that the major events of primary tumor metastasis, such as migration, invasion and angiogenesis, are enhanced by elevated insulin levels." (PMID 22226054, 2012). "However, both Go6976 and ML-7 diminished the insulin- and the glucose-mediated increase in tumour cell migration." (PMID 21179032, 2011). "In vitro studies support epidemiological data in that insulin increases the neoplastic proliferation of cell lines at both physiological and pharmacological doses and the insulin receptor is commonly expressed in human neoplasms." (PMID 21696633, 2011). "Furthermore, all tumour cells grown in medium containing additional 100 ng ml−1 of insulin (with 5.5 mM or 11 mM glucose) showed a pronounced increase of proliferation – displaying on average 20–40 percent higher proliferation rates." (PMID 21179032, 2011). "The supporting effect of insulin on tumor growth has been known since 1924, when Händel and Tadenuma described the nourishing effect of insulin on tumor tissue in an animal model, showing evidence that reducing insulin might reduce tumor growth." (PMID 22029671, 2011). "Almost all tumour cell lines revealed higher proliferation rates when cultured under hyperglycemic conditions, and all cell lines showed increased proliferation after the addition of 100 ng ml−1 insulin." (PMID 21179032, 2011). "Thus, genes targeted by HNF4α in the insulin signaling pathway as well as such related to cell death and tumour suppressor activity were identified." (PMID 21829439, 2011). "There is strong evidence that insulin promotes tumor cell growth via the IGF-IR and IR." (PMID 21437235, 2011). "These investigations indicated the possibility that such intracellular insulin may contribute to the pathogenesis of these neoplasias." (PMID 21457557, 2011). "As one of the last speakers, Eva Frei explained how albumin can be used to transfer and accumulate drugs or other compounds into tumour tissues; concerning the binding of insulin detemir (Levemir®) to albumin after subcutaneous injection, a paucity of data was noted in this respect." (PMID 21176129, 2010). "Subsequently, to test whether tumor development was sustained by insulin secretion we substituted islets with an insulin releasing pellet." (PMID 20436918, 2010). "Secondly, the higher endogenous levels of estrogen, insulin and triglycerides in obese women may accelerate the growth and metastasis of the tumor." (PMID 24281091, 2010). "Inhibition of insulin secretion from otherwise normal beta cells stimulated by sulfonylurea overdose demonstrates the ability of this drug to correct and prevent hypoglycaemia in beta cell hyperfunction outside of the tumour setting." (PMID 20615254, 2010). "Our results suggest that the PyMT oncogene cannot transdifferentiate β cells or any insulin-producing precursor to an exocrine phenotype or cause progressive neoplasia, regardless of the stage of development at which the oncogene is expressed." (PMID 19812721, 2009).
tumor (continued). "It is widely accepted that frequently elevated levels of insulin can stimulate tumour growth." (PMID 18447912, 2008). "Downregulation of Glut-4 activity and protein in fat cells has also been reported in tumour-bearing rats and this might lead to reduced insulin sensitivity in adipocytes." (PMID 17047651, 2006). "We hypothesized that the application of glucose, insulin, thyroid and potassium would awaken inert tumor infiltrating lymphocytes to destroy the tumor." (PMID 16111485, 2005). "The effects of bovine insulin (5.0 microgram/ml) human placental lactogen (10.0 microgram/ml) and human growth hormone (10.0 microgram/ml) on 3H-thymidine incorporation into DNA were determined on the cultured tumour slices." (PMID 698040, 1978). "Interestingly, we found deposits of insulin, which we suggest naming insulin bodies in two tumours." (PMID 41488993, 2026). "Thus, in most of the tumours, relatively few tumour cells contain insulin or GLP-1R." (PMID 41488993, 2026). "Furthermore, it has been suggested that APN is a potent inhibitor of the PI3K/AKT pathway, which may attenuate the growth of tumor cells stimulated by insulin and cytokines." (PMID 40620232, 2025). "Emerging evidence suggests that SGLT2 inhibitors may exert antineoplastic properties through multiple mechanisms, including metabolic reprogramming, the reduction of insulin and glucose availability in the tumor microenvironment, and attenuation of inflammation." (PMID 40364115, 2025). "Additionally, physical activity is known to lower blood glucose levels and improve insulin sensitivity, which may indirectly influence tumor growth." (PMID 40220151, 2025). "Furthermore, we discovered that insulin or IGF-1 binds to specific receptors on tumor cell membranes to regulate tumor growth and glucose metabolism by activating the PI3K/AKT/mTOR pathway in EC, meanwhile metformin can reduce plasma IGF-1 concentration thereby exerting anticancer activity." (PMID 38577616, 2024). "TZDs promote insulin sensitivity by activating peroxisome proliferator-activated receptor gamma (PPAR-γ) which has been found to suppress tumor growth in various types of tumor cells by the downregulation of proliferation and insulin resistance and induction of apoptosis." (PMID 39410536, 2024). "Combined with our research results, we speculate that the up-regulation of BID may regulate the internal energy metabolism of ccRCC by hindering the insulin signaling pathway, thereby increasing the demand for tumor biosynthesis and leading to tumor progression." (PMID 38767695, 2024). "However, if insulin signaling is facilitated in the tumor microenvironment, it may result in tumor growth." (PMID 39267853, 2024). "Furthermore, the deactivation of Men1 gene in murine glucagon-secreting alpha cells may result in the development of an insulin-hypersecreting tumor, whereas the deactivation of this gene in insulin-secreting beta-cells may result in glucagonoma." (PMID 39456803, 2024). "Notably, neoplasm resection retrieve insulin sensitivity, suggesting that exosomes from PDAC may play a role in insulin resistance, β cell failure, and lipolysis, which could explain the high prevalence of NOD in PDAC." (PMID 39596226, 2024). "Additionally, tumor cells express ImpL2 to suppress insulin signaling in host tissues." (PMID 38566182, 2024). "However, if an underlying factor of tumorigenesis was increased activation of proliferative pathways by altered insulin signaling in ChREBP-KO mice, one would expect to see differences between tumor development in normoglycemic mice and those with streptozotocin-induced insulin deficiency." (PMID 39518998, 2024). "Systemic insulin alterations may contribute to the anti-tumor effect." (PMID 37993438, 2023).